MTOR (mechanistic target of rapamycin kinase)
Diseases named in the same sentence as MTOR in open-access papers (continued):
Sharing a sentence is not in itself a finding about the gene and the disease.
bladder cancer (continued). "We concluded that the PI3K/AKT/mTOR signaling pathway might exert a significant effect on gypenoside-mediated antitumor effects in bladder cancer cells." (PMID 35402614, 2022). "Meanwhile, the mTOR signaling pathway was widely involved in bladder cancer development." (PMID 35615381, 2022). "In addition to discovering that the AKT/mTOR pathway is involved in regulating the progression of bladder cancer, we also identified downstream target proteins (c-Myc, SLC25A19, and ICAM5) of UCHL5 by RNA-Seq." (PMID 36428630, 2022). "For example, Tet can induce apoptosis of bladder cancer cells via the AMPK/mTOR axis." (PMID 33763489, 2021). "Finally, BCT-100 was demonstrated to induce autophagy and apoptosis via the ROS-mediated AKT/mTOR signaling pathway in bladder cancer cells." (PMID 33791071, 2021). "Using GSEA we identified differences between these clusters regarding cell cycle; oncogenic drivers (“bladder cancer” signature); complement activation and presence of immune cells (“hematopoietic cell lineage”); cell autophagy (“mTOR signaling” and “mitophagy” signatures); and mRNA surveillance." (PMID 34193272, 2021). "In addition, it was reported that inhibition of MTOR expression induced apoptosis of bladder cancer cells and inhibited cell cycle progression, cell growth, angiogenesis, and endothelial cell proliferation, indicating its therapeutic value." (PMID 33407469, 2021). "Collectively, our findings not only support the concept that ferroptosis is a type of autophagy-dependent cell death but imply that the combined application of ferroptosis inducers and mTOR inhibitors is a promising approach to improve therapeutic options in the treatment of bladder cancer." (PMID 34716292, 2021). "MiR-222 might modulate the PPP2R2A/Akt/mTOR axis to regulate the proliferation of bladder cancer cells and chemotherapeutic drug resistance." (PMID 34512152, 2021). "High expression of ULK3 is involved in bladder cancer and MTOR signaling pathway, among others." (PMID 34168974, 2021). "However, interaction of paclitaxel with miRNAs in bladder cancer and regulation of mTOR still requires substantial studies." (PMID 33292283, 2020). "The present study was designed to evaluate whether the natural compound, sulforaphane (SFN), combined with the mTOR inhibitor everolimus, could block the growth and proliferation of bladder cancer cells in the short- and long-term." (PMID 32512849, 2020). "The present findings reveal that chronic use of the mTOR inhibitor everolimus is associated with drug non-responsiveness, resulting in aggressive migratory activity of bladder cancer cells." (PMID 32759798, 2020). "Progressive bladder cancer growth is associated with abnormal activation of the mammalian target of the rapamycin (mTOR) pathway, but treatment with an mTOR inhibitor has not been as effective as expected." (PMID 32512849, 2020). "Several reports show that mTOR pathway activation may be closely involved in the tumorigenesis of bladder cancer and predict disease progression and poor survival." (PMID 32466578, 2020). "Nearly 40% bladder cancers have abrogated activation of the PI3K/AKT/mTOR pathway." (PMID 33292283, 2020). "Further, this result was observed in specific bladder cancer cells with PI3KCA and mTOR mutations." (PMID 32325639, 2020). "Since the mTOR pathway serves as a major autophagy regulator, we tested whether the CWS-loaded formulations could inhibit the activation of mTOR signaling in bladder cancer cells." (PMID 33302414, 2020). "Based on studies revealing that HDAC-inhibitors with SFN in particular counteract everolimus resistance in renal cancer cell lines, it was postulated that SFN might be an innovative candidate to complement mTOR inhibition in bladder cancer therapy." (PMID 32512849, 2020). "Deregulation of PI3K/Akt/mTOR signaling has been found in 40% of bladder cancers." (PMID 33292283, 2020).
bladder cancer (continued). "Moreover, several different approaches to successful bladder cancer treatment exists, such as the use of ganciclovir and mTOR (mammalian target of rapamycin) kinase inhibitors, IL-12 (interleukin-12) and COX-2 (cyclooxygenase-2)." (PMID 32392774, 2020). "The aim of this review is to discuss the interplay between PI3K/Akt/mTOR, miRNAs, and natural compounds and emphasize the importance of miRNAs as biomarkers and resveratrol, curcumin and paclitaxel as a possible therapeutic approach against bladder cancer." (PMID 33292283, 2020). "The PI3K/AKT/mTOR pathway is a potential therapeutic target for bladder cancer." (PMID 32325639, 2020). "Therefore, recognizing and targeting genetic variations of the PI3K/AKT/mTOR pathway has an important clinical implication for bladder cancer prognosis." (PMID 31665050, 2019). "Indeed, preclinical studies using bladder cancer cell models or xenografted mice demonstrated that inhibition of mTOR by everolimus inhibited bladder cancer cell growth in vitro and in xenografted mice." (PMID 29454321, 2018). "Previous reports investigating PI3K pathway inhibition in bladder cancer have demonstrated that cells possessing activating mutations in PIK3CA are selectively sensitive to PI3K or AKT inhibition, while TSC1 or mTOR mutations contribute to sensitivity to rapalogs." (PMID 29357370, 2018). "Puerarin suppress bladder cancer cell proliferation through the mTOR/p70S6K signaling pathway." (PMID 30666203, 2018). "In addition, AKT, the key component of PI3K/AKT/mTOR signaling pathway, is verified to be frequently activated in numerous kinds of human cancers including bladder carcinoma." (PMID 27893422, 2017). "Additionally, research has focused on mTOR inhibition as a potential target for chemoprevention in bladder cancer." (PMID 28423681, 2017). "Interestingly, compared with Que, TFQ activated AMPK and inactivated mTOR with significantly greater potencies in all of the tested bladder cancer cell lines." (PMID 29069736, 2017). "The effect of mTOR signaling has also been observed in bladder cancer." (PMID 29214525, 2017). "TFQ may be a useful small molecule candidate for the treatment of bladder cancer via AMPK/mTOR signaling pathway." (PMID 29069736, 2017). "Although the mechanistic target of rapamycin (mTOR) might be a promising molecular target to treat advanced bladder cancer, resistance develops under chronic exposure to an mTOR inhibitor (everolimus, temsirolimus)." (PMID 29299126, 2017). "In addition, PI3K and mTOR have prognostic/predictive value and represent valuable therapeutic targets in bladder cancer." (PMID 28373897, 2017). "For prognostic value, some studies indicated the low miR-100 expression in bladder cancer predicts unfavorable prognosis and it might regulate tumor metastasis or other related processes about tumorigenesis by inhabiting mTOR." (PMID 28977982, 2017). "Also, in vitro research using Rhodiola rosea extract has shown to inhibit mTOR and decrease growth of bladder cancer." (PMID 28423681, 2017). "Amplification and/or mutations of several key genes regulating this pathway, such as PIK3CA (encoding the p110α subunit), PIK3R1(encoding the p85α subunit), AKT, and PTEN, are well-known mechanisms involved in the activation of PI3K/Akt/mTOR pathway in bladder cancer." (PMID 26931119, 2016). "Importantly, our study highlighted for the first time a novel miR‐222/PPP2R2A/Akt/mTOR axis that regulates CDDP sensitivity in bladder cancer." (PMID 26800397, 2016). "In the present study, we observed that overexpression of miR‐222 in bladder cancer cells suppresses autophagy; this suppression might be mediated by the activation of the Akt/mTOR signalling pathway." (PMID 26800397, 2016).
bladder cancer (continued). "Therefore, our data demonstrated that the PPP2R2A/Akt/mTOR axis played a regulatory role in the miR‐222‐induced proliferation of bladder cancer." (PMID 26800397, 2016). "We observed a significant increase in the p70S6K phosphorylation levels in miR‐222‐transfected T24 and 5637 cells, indicating that miR‐222 could activate the mTOR pathway in bladder cancer cells." (PMID 26800397, 2016). "We observed a significant activation of Akt/mTOR in miR‐222‐overexpressing bladder cancer cells." (PMID 26800397, 2016). "Thus, GOLPH3 is likely to play important roles in bladder cancer progression via modulating AKT/mTOR signaling, and it is a novel prognostic biomarker and promising therapeutic target for bladder cancer." (PMID 26375441, 2015). "Knockdown of GOLPH3 decreased the proliferation, migration and invasion of bladder cancer cells and the tumor growth in xenograft mice, which may be associated with GOLPH3 modulation of AKT/mTOR signaling." (PMID 26375441, 2015). "Based on these observations we hypothesize that Tn and/or STn may act synergistically with the mTOR pathway to drive bladder cancer progression." (PMID 26569621, 2015). "The following pathways of interest were shown to be significantly enriched: bladder cancer, cytokine-cytokine receptor interaction, mTOR signaling pathway, cell adhesion molecules, toll-like receptor pathway, B cell receptor signaling pathway and VEGF signaling pathway." (PMID 24932473, 2014). "However, further demonstration of the regulation of mTOR by microRNA-99a in bladder cancer cells is required." (PMID 25014919, 2014). "However, no study has tested in detail the synergistic effect between cisplatin and mTOR inhibitors in human bladder cancers, especially for cisplatin-resistant tumors." (PMID 24969552, 2014). "The inhibition of mTOR was found to decrease in vitro and in vivo bladder cancer cell growth." (PMID 25014919, 2014). "Our data show that the mTOR gene was downregulated by miR-100 in bladder cancer cell lines." (PMID 25493074, 2014). "While these observations emphasize the important role that the activation of PI3K/AKT plays in the cancer radioresistance, we demonstrate that blocking the PI3K/AKT/mTOR pathway with RAD001 appears as a valuable mean to enhance the efficacy of radiation treatment in bladder cancer cells." (PMID 23799002, 2013). "Moreover, inhibition of mTOR signaling pathway in bladder cancer models demonstrated remarkable anti-cancer activity both in vitro and in vivo, making it an attractive target for cancer therapeutics." (PMID 24351837, 2013). "Since radiation was shown to activate the PI3K/Akt survival/growth pathway which may be responsible for the cell death escape and radioresistance, concurrent mTOR inhibition may potentially overcome resistance to radiation in bladder cancer." (PMID 23799002, 2013). "Interestingly, remarkable differences in sensitivity to mTOR inhibition were noted among nine human bladder cancer cell lines." (PMID 23799002, 2013). "It has been described that hypoxia may regulate mTOR induction in bladder cancer." (PMID 40353763, 2025). "Thus, we hypothesize that inhibition of the mTOR pathway in bladder cancer cells is a secondary phenomenon following mitochondrial stress and TRAIL regulation." (PMID 40353763, 2025). "However, a previous study conducted on bladder cancer showed similar association between CDCA5 and PI3K/AKT/mTOR pathway, which supports our hypothesis." (PMID 36428736, 2022). "AMPK/mTOR pathway could activate autophagy and mitochondrial dysfunction in bladder cancer cells." (PMID 34512152, 2021). "Therefore, sulforaphane may hold potential for treating bladder carcinoma in patients with resistance to an mTOR inhibitor." (PMID 32512849, 2020).
bladder cancer (continued). "Taken together, the results of the present study demonstrated the anticancer effect of CTT on bladder cancer cells, which might be associated with the downregulation of PI3K/AKT/mTOR and NF-κB signalling pathway proteins, and this inhibition was mediated by the induction of PTEN." (PMID 31897244, 2020). "Therefore, the PI3K/Akt/mTOR pathway might be a potential target for the treatment of bladder cancer." (PMID 31897244, 2020). "Currently, everolimus is the only mTOR inhibitor approved by the U.S. Food and Drug Administration to treat breast cancer, advanced renal carcinoma, pancreatic neuroendocrine tumor and subependymal giant-cell astrocytoma, thus opening this therapeutic approach for bladder carcinoma as well." (PMID 32759798, 2020). "Hence, combining the mTOR inhibitor everolimus with a naturally derived epigenetic drug such as SFN may provide an innovative strategy in treating bladder cancer by acetylating histones H3 and H4 and concomitantly elevating the tumor suppressor p19." (PMID 32512849, 2020). "Therefore, chronic use of temsirolimus may reactivate mTOR and not only accelerate bladder cancer cell proliferation but also force the tumor cell invasion cascade." (PMID 31167517, 2019). "Therefore, long-term suppression of mTOR could re-activate the mitotic machinery as evidenced by a profound increase in the S- and G2/M-phase in drug resistant bladder cancer cells." (PMID 31167517, 2019). "Therefore, we speculated that the synergistic action of these two drugs might affect bladder cancer cells by inactivation of Akt/mTOR/MAPK pathway." (PMID 28746469, 2017). "In addition, targeting mTOR pathways in post-cisplatin bladder cancer has been tested, but has not been associated with improved clinical outcome." (PMID 27823983, 2016). "Therefore, targeting PI3K/Akt/mTOR might be an effective strategy in the treatment of bladder cancer." (PMID 26931119, 2016). "Consequently, the role of mTOR inhibitors is now being evaluated in bladder cancer." (PMID 25515347, 2014). "Notably, treatment with mTOR inhibitors has been observed to enhance the therapeutic efficacy of cisplatin and gemcitabine in bladder cancer cell lines, and impair tumour progression when administered intravesically in a bladder cancer mouse model." (PMID 25202348, 2014). "One signaling pathway that has recently drawn much attention for this purpose is the PI3K/AKT/mTOR axis and abnormal activation of this pathway has been reported to play an important role in progression, metastasis, and also chemoresistance in a variety of tumors including bladder cancer." (PMID 24969552, 2014). "It is also important to note that no matter what kind of natural product it is, its regulation of bladder cancer survival and metabolism mainly occurs by regulating the MAPK family signal transduction pathway and the PI3K/Akt/mTOR pathway." (PMID 41596251, 2026). "In our study, we investigated how phosphoinositide 3‐kinase (PI3K)/AKT/mTOR pathway inhibitors (TAK‐228, everolimus and TAK‐117) affect PD‐L1 expression and function in preclinical bladder cancer cell models." (PMID 39258533, 2025). "The phosphoinositide 3 kinase/protein kinase B/mammalian target of rapamycin (PI3K/AKT/mTOR) pathway is crucial, as it regulates cell growth, proliferation, and survival, and its de-regulation has been reported in 40% of bladder cancers." (PMID 40277814, 2025). "A recent study highlighted the considerable upregulation of TRIM59 in recurrent bladder cancer, involving the F-actin/ITGB8/TRIM59/AKT/mTOR/glycolysis pathways." (PMID 40796729, 2025). "Mechanistically, inhibition of the mTOR pathway and SREBP activity was found to reduce FADS2 expression and promote ferroptosis in bladder cancer." (PMID 40682485, 2025). "Metformin was reported to inhibit bladder cancer cell migration and growth and promote apoptosis via the inhibition of both AKT and mTOR proteins." (PMID 40868065, 2025).
bladder cancer (continued). "In one preclinical study, CAFs induced cisplatin resistance in bladder cancer cells through exosomal miR-146a-5p, which activated the STAT3 and mTOR signaling pathways by targeting ARID1A and PRKAA2." (PMID 39757995, 2025). "ADAMTS9-AS1 promotes the invasion and migration of bladder cancer cells and negatively regulates the apoptosis and autophagy of bladder cancer cells, possibly through the PI3K/AKT/mTOR signaling pathway." (PMID 40183046, 2025). "In bladder cancer, up to 40% of tumors exhibit constitutive activation of the PI3K/AKT/mTOR pathway." (PMID 41287122, 2025). "Temsirolimus, an mTOR inhibitor approved by the FDA for advanced renal cell carcinoma, has demonstrated modest antitumor activity in clinical studies for bladder cancer." (PMID 41438986, 2025). "In bladder cancer, miR-222 attenuated cisplatin-induced cell death by targeting the PPP2R2A/Akt/mTOR axis." (PMID 39951446, 2025). "mTOR inhibition with TAK‐228 can increase PD‐L1 levels, potentially impacting the specific immune response against bladder cancer cell lines." (PMID 39258533, 2025). "Research on inhibitors targeting the PI3K/AKT/mTOR pathway and VEGF inhibitors has also achieved notable progress in bladder cancer." (PMID 41438986, 2025). "The stable detection ability of ctDNA makes it of great value in guiding the emerging targeted therapy and immunotherapy for metastatic bladder cancer, especially in terms of targeted changes in the MAPK/ERK and PI3K/AKT/mTOR pathways." (PMID 40191434, 2025). "Specifically, patients with bladder cancer having lower levels of mTOR and STAT3 were predicted to have a longer survival compared to those with high mTOR and STAT3 levels." (PMID 38886756, 2024). "mTOR and STAT3 were selected as the two gene targets for a knockdown in our pilot system based on bladder cancer patient data." (PMID 38886756, 2024). "Last, cisplatin-resistant human bladder cancer cells were also shown to be more sensitized with combined treatment of HSP90 and a PI3K/mTOR dual inhibitor, which was mediated by increased G1 arrest and apoptosis." (PMID 38475728, 2024). "In concert with downregulated PI3K/Akt/mTOR signaling, ISO has been previously reported to increase the expression and activity of FOXO1 and FOXO3a in bladder cancer cells." (PMID 38339062, 2024). "New targets to hit the major signalling pathways that are upregulated in bladder cancer, such as the PI3K/AkT/mTOR pathway, are urgently needed, with only one drug approved so far, Erdafitinib." (PMID 38338835, 2024). "Downregulation of PKM2 reduces FASN expression and inhibits bladder cancer cell growth by significantly reducing the phosphorylation of both AKT and mTOR and inactivating the AKT/mTOR/SREBP1c signaling pathway." (PMID 36969840, 2023). "In bladder cancer cells, miR-99a-5p enhanced RAD001-induced apoptosis in human bladder uroepithelial carcinoma cells (5637 and T24 cells) by targeting mTOR as a tumour suppressor." (PMID 37081566, 2023). "This agent also reduced the cellular viability and migration of TSGH-8301 human bladder cancer cells (10 μM, 24 h), which coincided with a reduction in p-PI3K, p-AKT, and p-mTOR (5–10 μM)." (PMID 38132936, 2023). "Everolimus treatment, an mTOR inhibitor, with simultaneous OTUD5 knockdown seems to be an ideal strategy for bladder cancer treatment." (PMID 37497216, 2023). "Research showed that NaB inhibited bladder cancer cell migration and induced AMPK/mTOR pathway-activated mitophagy and ROS overproduction through the miR-139-5p/Bmi-1 axis, while ROS overproduction contributed to NaB-induced cysteine-dependent apoptosis." (PMID 37686278, 2023).